RNU7-165P (RNA, U7 small nuclear 165 pseudogene)
Gene: Small nuclear RNA gene on chromosome 10 (113,353,425 to 113,353,484, forward strand). Ensembl gene ENSG00000238380.
Homologues: Orthologues: chimpanzee U7 (98% identical), macaque U7 (78% identical). Paralogues in human: RNU7-37P (83% identical), RNU7-70P (82% identical), RNU7-104P (80% identical), RNU7-123P (80% identical), RNU7-73P (80% identical), RNU7-88P (80% identical), RNU7-94P (80% identical), RNU7-1 (78% identical), RNU7-120P (78% identical), RNU7-129P (78% identical), RNU7-130P (78% identical), RNU7-21P (78% identical), and 141 more.